CDC42EP4 (CDC42 effector protein 4)
Description:
Probably involved in the organization of the actin cytoskeleton. May act downstream of CDC42 to induce actin filament assembly leading to cell shape changes. Induces pseudopodia formation, when overexpressed in fibroblasts.
Synonyms: BORG4; CEP4; KAIA1777; MGC3740; MGC17125
Tractability: Antibody: its Gene Ontology location is reachable by antibodies, with high confidence; UniProt places it where antibodies can reach, with medium confidence; the Human Protein Atlas places it where antibodies can reach. PROTAC: ubiquitination databases record sites on it; its protein half-life has been measured.
Gene: Protein-coding gene on chromosome 17 (73,283,624 to 73,312,005, reverse strand). Ensembl gene ENSG00000179604.
Subcellular location: Endomembrane system; Cytoplasm, cytoskeleton
Subcellular location (Human Protein Atlas): Actin filaments; Microtubules; Plasma membrane
Pathways (Reactome):
Signal Transduction: CDC42 GTPase cycle; RAC1 GTPase cycle; RAC2 GTPase cycle; RHOQ GTPase cycle
Gene Ontology:
Molecular function: protein binding; RNA binding; small GTPase binding
Biological process: positive regulation of pseudopodium assembly; regulation of cell shape; positive regulation of actin filament polymerization; Rho protein signal transduction
Cellular component: actin cytoskeleton; adherens junction; microtubule cytoskeleton; cytoplasm; cytoskeleton; cytosol; plasma membrane; endomembrane system; phagocytic vesicle
Genetic constraint (gnomAD): Loss-of-function variants: 7 observed, 8.16 expected, observed/expected ratio (o/e) 0.86, 90% interval 0.49 to 1.58. That is too few expected variants to judge how well the gene tolerates losing a copy. Missense variants: 490 observed, 510.61 expected, observed/expected ratio (o/e) 0.96, 90% interval 0.89 to 1.03. Synonymous variants: 230 observed, 227.09 expected, observed/expected ratio (o/e) 1.01, 90% interval 0.91 to 1.13.
Homologues: Orthologues: macaque CDC42EP4 (97% identical), pig CDC42EP4 (88% identical), guinea pig CDC42EP4 (81% identical), mouse Cdc42ep4 (77% identical), rat Cdc42ep4 (75% identical), tropical clawed frog cdc42ep4 (48% identical), zebrafish cdc42ep4b (46% identical), zebrafish cdc42ep4a (40% identical), dog VCF1 (13% identical). Paralogues in human: CDC42EP1 (26% identical), CDC42EP5 (19% identical), CDC42EP2 (18% identical), CDC42EP3 (16% identical), C15orf62 (11% identical).
Diseases named in the same sentence as CDC42EP4 in open-access papers:
CDC42EP4 is named in the same sentence as 10 diseases in open-access papers, as found by Europe PMC text mining. Sharing a sentence is not in itself a finding about the gene and the disease. The quoted sentences say what the papers report.
breast cancer (2 papers, 2015 to 2021). A primary or metastatic malignant neoplasm involving the breast. "Increasing numbers of genes involved in breast cancer have been found, including Ets-1 (E-twenty-six-1), PKC (protein kinase C), CEP4 (CDC42 effector protein 4), Her2 (erb-b2 receptor tyrosine kinase 2), ALDH1 (aldehyde dehydrogenase 2), FOXA1 (forkhead box A1) and HOXD10 (homeobox D10)." (PMID 25739083, 2015).
glial tumors (2 papers, 2017 to 2023). "In recent years, limited reports have shown that CDC42EP3, a member of the same family as CDC42EP4, is highly expressed in gastric cancer, gliomas, and colorectal cancer." (PMID 38153517, 2023).
behavioral disorders (1 paper, 2018). "Some candidates have been linked to intellectual disability (ID), such as CRBN, GPKOW, HERC1 and KCNA4, or to other behavioral disorders, such as CDC42EP4 and SLITRK5." (PMID 30102725, 2018).
Stroke (1 paper, 2023). Sudden impairment of blood flow to a part of the brain due to occlusion or rupture of an artery to the brain. "Conversely, increased transcript expression of Arf6 and Cdc42ep4 was observed in old and young post-stroke BBB." (PMID 36855111, 2023).
cancer (3 papers, 2017 to 2023). A tumor composed of atypical neoplastic, often pleomorphic cells that invade other tissues. "However, the link between CDC42EP4 expression and cancer remains unreported." (PMID 38153517, 2023).
tumor (1 paper, 2023). "To date, the role of CDC42EP4 in tumor progression remains unexplored." (PMID 38153517, 2023). "To date, only a few reports have indicated a strong association between CDC42EP3 and tumorigenesis and progression, with no studies exploring the role and mechanisms of CDC42EP4 in tumor progression." (PMID 38153517, 2023).
CDC42EP4 also shares sentences with these, for which no sentence is quoted: colorectal cancer (1 paper); gastric cancer (1); gliomas (1); Intellectual disability (1).